WT1 (WT1 transcription factor)
Diseases named in the same sentence as WT1 in open-access papers (continued):
Sharing a sentence is not in itself a finding about the gene and the disease.
Sepsis (4 papers, 2017 to 2025). Sepsis is defined as life-threatening organ dysfunction caused by a dysregulated host response to infection. "Monozygotic twins with congenital nephrotic syndrome caused by a WT1 mutation have been reported to have died due to sepsis and extensive thrombosis of central venous system and sepsis and sudden heart failure at ages 23 weeks/13.5 months, respectively." (PMID 34299295, 2021). "Another mechanism of modulation of WT1 that has been observed in experimental mice during the sepsis is the decrease of nuclear WT1 in podocytes and was associated with transcriptional suppression of nephrin and cause albuminuria." (PMID 28299339, 2017). "This multicentric observational prospective study aims to evaluate blinding the genetic expression kinetics of different molecules involved in the inflammatory process, IL10, PD1 and WT1, to search for a possible molecular predictive marker of sepsis." (PMID 41013722, 2025). "Lastly, in a lipopolysaccharide murine sepsis model, renal expression of WT1/nephrin was decreased, inducing renal damage." (PMID 35453662, 2022). "Analysing the gene expression profiles of IL10, PD1, and WT1 in patients who develop sepsis after cardiac surgery may offer critical insights into the mechanisms driving immune dysregulation in this setting." (PMID 41013722, 2025). "The role of Wilms Tumor 1 (WT1) in sepsis is less well defined, although recent evidence suggests that WT1 is involved in hematopoietic differentiation, cytokine signaling, and immune cell regulation, making it a candidate of interest in the study of sepsis-related immune alterations." (PMID 41013722, 2025). "Different studies have been conducted on genes coding for inflammatory cytokines whose could predispose to the development of sepsis [e.g., IL-10 PD1 and WT1]." (PMID 41013722, 2025). "However, the results obtained from the analysis of WT1 showed an interesting trend; however, it is evident that in patients who developed sepsis, WT1 was over-expressed compared to patients who did not develop sepsis (FC = 0.67 vs FC = 0.079, respectively) (p < 0.05)." (PMID 41013722, 2025).
T-cell acute lymphoblastic leukemia (4 papers, 2014 to 2023). Acute lymphoblastic leukemia of T-cell origin. "Two cases (PD40822 and PD40836) involved clonal frameshifts in genes associated with T-cell ALL (PTPN2 p.A108fs∗5 and WT1 p.V371fs∗14, respectively)." (PMID 36867579, 2023).
thymoma (4 papers, 2017 to 2023). A neoplasm arising from the epithelial cells of the thymus. "A WT-1 peptide vaccine was evaluated in a phase II trial in patients with relapsed/refractory, HLA-A*24:02 positive thymoma, or TC expressing Wilms’ tumor-1 (WT-1) protein, which was found to be overexpressed in TETs (thymomas: 80%; TCs 84.6%)." (PMID 38067278, 2023). "In a study of 13 thymic carcinoma and 5 thymoma tumor samples from advanced, pre-treated TETs, the overexpression of WT1 was detected in 84.6% of thymic carcinomas and 80% of thymomas." (PMID 35565190, 2022). "Genes involved in histone modification (BAP1, 13%; SETD2, 11%; ASXL1, 4%), chromatin remodelling (SMARCA4, 4%), and DNA methylation (DNMT3A, 7%; TET2, 4%; WT1, 4%) were frequently mutated in thymic carcinomas, but not thymomas." (PMID 35884448, 2022).
adenoma (3 papers, 2022 to 2023). A neoplasm arising from the epithelium. "Metastatic follicular carcinoma of the thyroid shows TTF-1 expression, whereas metanephric adenoma shows tightly packed tubules lined by uniform cuboidal cells with occasional presence of papillary structures and diffuse positivity for WT1." (PMID 34514572, 2022). "In addition to WT1, we also found carcinoma-specific upregulation of LGALS3 (galectin-3) and UCHL1 (PGP9.5) (also upregulated in adenoma), which has been suggested as an IHC marker in parathyroid carcinoma." (PMID 37121965, 2023).
Alzheimer disease (3 papers, 2009 to 2025). A progressive, neurodegenerative disease characterized by loss of function and death of nerve cells in several areas of the brain leading to loss of cognitive function such as memory and language. "Moreover, WT1 might have a role in neurodegeneration, observed in Alzheimer's disease brain." (PMID 19737418, 2009).
astrocytoma (3 papers, 2004 to 2020). "Grade IV astrocytomas demonstrated constantly significant associations between WT1 score and all tested variables." (PMID 32856872, 2020). "As WT1 increases significantly with degree of malignancy in astrocytomas, it was linked to poor prognosis." (PMID 32856872, 2020). "The reverse also seems true, as IHC analysis of FFPE tumor sections from astrocytoma animal models transduced with anti-WT1 shRNA revealed that the Ki67 proliferation index was higher in the control tumors." (PMID 32856872, 2020). "In this way, silencing of WT1 has been suggested to promote a more differentiated phenotype of astrocytoma cells with a lower proliferative capacity." (PMID 25474318, 2014). "Furthermore, Manocha and Jain (2019), attributed the lower WT1 scores in grade II astrocytomas to the high frequency of IDH1 positivity." (PMID 32856872, 2020). "This was in league with other studies reporting a significant increase in mean WT1 score across astrocytoma grades, with a frequent assignment of higher WT1 scores to grade IV tumors." (PMID 32856872, 2020). "Therefore, Manocha and Jain (2019), presumed WT1 utility in differentiating high and lowgrade astrocytomas in challenging biopsies." (PMID 32856872, 2020). "In low-grade astrocytomas (I and II), all WT1 negative cases and most WT1 score +1 were older than the median age for the corresponding grade." (PMID 32856872, 2020).
Azoospermia (3 papers, 2013 to 2019). Absence of any measurable level of sperm,whereby spermatozoa cannot be observed even after centrifugation of the semen pellet. "The observation of these predicted deleterious mutations specifically in the NOA population strongly indicates that WT1 is also important for spermatogenesis in human and that WT1 mutation plays an etiologic role in azoospermia." (PMID 23935527, 2013). "Non-obstructive azoospermia (NOA) patients carried the WT1 mutant, and WT1 loss of function in mouse SCs led to BTB structural damage, which in turn resulted in GCs death." (PMID 31171774, 2019). "The testes histology of human non-obstructive azoospermia (NOA) was very similar to Wt1-deficient testes." (PMID 23935527, 2013). "In the present study, we detected Wt1 missense mutations in men with non-obstructive azoospermia (NOA)." (PMID 23935527, 2013). "Also, six missense mutations within WT1, were detected in 529 human patients with non-obstructive azoospermia, indicating a strong association between WT1 mutation and non-obstructive azoospermia." (PMID 24983376, 2014). "In the present study, six missense mutations of WT1 gene were detected in 529 human patients with non-obstructive azoospermia (NOA), indicating a strong association between WT1 mutation and NOA." (PMID 23935527, 2013). "To determine whether WT1 mutation is associated with spermatogenic defects in humans, following exonic capture we sequenced (mean depth of 43×) the exons of WT1 in 529 non-obstructive azoospermia (NOA) patients and 709 men with proven fertility." (PMID 23935527, 2013).
biliary tract cancer (3 papers, 2021 to 2025). "WT1 mutations are present in 68%-80% of biliary tract cancers, and while the clinical relevance in biliary tract cancer is still under investigation, similar mutations have been associated with poor prognosis in other cancers like testicular, breast, and head and neck cancers." (PMID 40013133, 2025). "In one study using a WT1 peptide vaccine and gemcitabine combination therapy for pancreatic and biliary tract cancers, including eight patients with advanced CCA and eight with advanced GBC, the disease control rate in biliary tract cancer was 50% and median overall survival was 278 days." (PMID 34440865, 2021).
Erythema (3 papers, 2022 to 2024). Redness of the skin, caused by hyperemia of the capillaries in the lower layers of the skin. "A previous report indicated that erythema at the vaccination site (30 mm in longitudinal diameter or more) is associated with induction of antitumor immunity and clinical benefits from the WT1/MUC1-DC vaccine." (PMID 38336778, 2024). "In line with our safety results, there are hardly any reports about treatment-related toxicity due to WT1 vaccination approaches except mild erythema at the sites of injection." (PMID 35476127, 2022).
glomerulonephritis (3 papers, 2017 to 2023). A renal disorder characterized by damage in the glomeruli. "Western blot analysis demonstrated a disappearance of WT-1 protein in the kidneys of aged NZB/WF1 mice (42 weeks old), the ones suffered from severe glomerulonephritis as compared to the pre-diseased ones (16 weeks old)." (PMID 30696480, 2019). "Furthermore, podocyte loss and glomerular hypertrophy were similar in both groups after NTS-induced glomerulonephritis, as showed by the lack of difference in WT1-positive nuclei and glomerular area." (PMID 36813870, 2023).
gonadal dysgenesis (3 papers, 2021 to 2025). A congenital disorder characterized by the presence of extremely hypoplastic gonads preventing the development of secondary sex characteristics. "During the last two years, six distinct WT1 mutations have been described in 46,XX TDSD/OTDSD patients with phenotypes completely different from those associated with earlier reported WT1 mutations (46,XY gonadal dysgenesis in Denys–Drash or Frasier syndrome)." (PMID 34943163, 2021).
hemangioma (3 papers, 2021 to 2025). A benign vascular lesion characterized by the formation of capillary-sized or cavernous vascular channels. "Moreover, tumor cells of lymphangioma and hemangioma are positive for immunohistochemical markers, such as CD31 and CD34, and negative for mesothelial markers such as calretinin, D2–40, and WT-1, which is helpful in distinguishing them from AT." (PMID 38115250, 2023).
IgA nephropathy (3 papers, 2012 to 2022). "The number of glomerular WT1(+)γH2AX(+)cells, which indicate podocytes with DNA DSBs, was increased in IgA nephropathy compared to controls (p = 0.0024)." (PMID 31937846, 2020). "ClC-5 expression was studied using Real-time PCR in manually- and laser-microdissected biopsies from patients with type 2 diabetes (n 37) and IgA nephropathy (n 10); in biopsies of membranous glomerulopathy (MG) (n 14) immunohistochemistry for ClC-5 (with morphometric analysis) and for WT1 was done." (PMID 23029130, 2012).
infarction (3 papers, 2012 to 2022). A localised pathological necrosis of tissue resulting from obstruction of the blood supply usually by a thrombus, an embolus, or vascular torsion. "At three days post-MI both Wt1 and Cre mRNA expression were detected in the epicardium overlaying the border zone of the infarct as well as the infarction itself, albeit at lower levels, and was absent from epicardium located remotely of the infarct." (PMID 23028582, 2012). "We have previously reported WT1 expression in pericardial ADSC as an injury-responsive element that, once activated, boosted reparative activity in the rat model of infarction." (PMID 35101092, 2022).
inflammatory myofibroblastic tumor (3 papers, 2020 to 2025). A multinodular intermediate fibroblastic neoplasm that arises from soft tissue or viscera, in children and young adults. "Besides, expression of WT1 and D240 in the majority of inflammatory myofibroblastic tumors should be considered in the diagnostic work up to minimize misdiagnoses." (PMID 32430041, 2020).
invasive breast carcinoma (3 papers, 2012 to 2022). A carcinoma that infiltrates the breast parenchyma. "Secondly, we analysed a locally derived cohort of invasive breast cancer samples (n = 44) using isoform-specific assays: quantitative RT-PCR was first performed using primers targeting exon 7/8 of WT1, in order to amplify all the known isoforms." (PMID 28345629, 2017).
liver fibrosis (3 papers, 2020 to 2025). "Wt1+ fibroblasts displayed distinct expression of genes, such as Scara5, Fbln2, Adgrd1, and Osr1 (encoding the odd-skipped related transcription factor 1) that has been linked to liver fibrosis, and mesenchymal collagen production (Fig. EV3E)." (PMID 40954217, 2025). "A recent study using a mouse model has demonstrated that Wilms tumor 1 (Wt-1) expressing MCs can give rise to HSCs and myofibroblasts during liver fibrosis via mesothelial-mesenchymal transition." (PMID 32284794, 2020). "In liver fibrosis, WT1 binds to the HAS2 promoter and stimulates the transcription of HAS215." (PMID 35662287, 2022).
lupus (3 papers, 2018 to 2024). "In this study, we found the decreasing expression of WT-1 and nephrin by immunofluorescence and qRT-PCR in kidneys of both pristane and imiquimod-induced lupus-like model mice." (PMID 29988544, 2018). "In addition, expression of WT1, a marker of podocyte, was significantly decreased in vehicle-treated lupus mice, while baicalein gradually enhanced WT1 expression." (PMID 31023362, 2019).
lymphoid leukemia (3 papers, 2007 to 2022). A malignant lymphocytic neoplasm of B-cell or T-cell lineage involving primarily the bone marrow and the peripheral blood. "Abundant expression of WT1 proteic transcripts has been noted in hematological malignancies (the bulk of acute myeloid/lymphoid leukemias) and in almost every subtype of solid adult tumor." (PMID 35453662, 2022). "Indeed, the poor prognosis of AML and lymphoid leukemia patients is strongly related to WT1 overexpression of WT1 on tumor cells." (PMID 34412685, 2021).
myeloproliferative neoplasm (3 papers, 2016 to 2020). A clonal hematopoietic stem cell disorder, characterized by proliferation in the bone marrow of one or more of the myeloid (i.e., granulocytic, erythroid, megakaryocytic, and mast cell) lineages. "The findings of both dysplastic and proliferative features in the Flt3+/ITD/Wt1+/R394W mice are compatible with a myelodysplastic disorder/myeloproliferative neoplasm (MDS/MPN)." (PMID 30450160, 2018).
papillary thyroid carcinoma (3 papers, 2016 to 2026). "In summary, WT1 contributes to cell proliferation, migration and growth of papillary thyroid carcinoma through augmented activation of the AKT/mTOR axis and ERK/p65 signaling pathway." (PMID 35123502, 2022). "And schematic of mechanism of BRAF-activated WT1 contributes to cancer growth and regulates autophagy and apoptosis in papillary thyroid carcinoma." (PMID 35123502, 2022).
peritoneal carcinoma (3 papers, 2016 to 2025). A peritoneum cancer that is located in the inside of the abdomen. "Most patients in this study had confirmed WT1 positive tissue diagnoses of serous ovarian, tubal, or primary peritoneal cancer." (PMID 31319587, 2019). "We chose to explore the presence/absence of the Wilm’s Tumour protein, WT1 in CCs as nuclear/cytoplasmic expression of WT1 has 96% specificity and 100% sensitivity as a marker in serous tubal, ovarian, peritoneal cancer." (PMID 31319587, 2019). "The WT-1 immunostaining pattern in the present peritoneal carcinoma was focal and weak; thus, more reliable information was required to make a conclusive diagnosis." (PMID 27842566, 2016).
Peritoneal Fibrosis (3 papers, 2018 to 2025). Disorder characterized by a wide range of structural changes in PERITONEUM, resulting from fibrogenic or inflammatory processes. "Conditional deletion of the Tgfbr2 gene in WT1+ mesothelial cells, treatment with the TGF-β1-blocking peptide p144 or p17, or use of mutant mice deficient in Smad3 all significantly attenuate the fibrotic response in (both) visceral and parietal mesothelium in several peritoneal fibrosis models." (PMID 30345394, 2018).
premature ovarian failure (3 papers, 2016 to 2025). "The mutant Wt1 mice exhibited ovarian follicle development defects which were similar to premature ovarian failure." (PMID 40916072, 2025). "For the regulation of WT1, Epg5 (ectopic P-granules 5 autophagy tethering factor), whose deleted mice showed a phenotype similar to that of patients with premature ovarian failure, promotes WT1 degradation via p62 in granulosa cells." (PMID 36979065, 2023).
Proteinuria (3 papers, 2013 to 2022). Increased levels of protein in the urine. "Proteinuria is the most frequent and pervasive manifestation of the WT1 mutation from birth through childhood to adulthood." (PMID 35498778, 2022). "Higher levels of WT1 observed in Proteinuria group led us to determine its relation with urine protein excretion in diabetic patients." (PMID 23544132, 2013). "WT1 was detected in all the patients in Proteinuria group (100%)." (PMID 23544132, 2013). "Enhanced detection (50%) and higher levels WT1 in Non-Proteinuria group compared to healthy controls might indicate very early renal injury." (PMID 23544132, 2013). "Furthermore, Proteinuria group had significantly higher levels of WT1 compared to Non-Proteinuria and control groups (p<0.001)." (PMID 23544132, 2013).
steroid-resistant nephrotic syndrome (3 papers, 2017 to 2025). Nephrotic syndrome, occurring in the pediatric population, in which proteinuria does not normalize with administration of steroids; this condition is unresponsive to a minimum of four weeks administration of oral corticosteroids. "These included 3 cases of autosomal dominant tubulointerstitial kidney disease (UMOD), 3 cases of hereditary FSGS/steroid resistant nephrotic syndrome (INF2 × 2, WT1 × 1), 3 cases of nail-patella-like renal disease (LMX1B), and 2 cases of MYH9-related disease." (PMID 40753325, 2025).
Stroke (3 papers, 2016 to 2020). Sudden impairment of blood flow to a part of the brain due to occlusion or rupture of an artery to the brain. "Furthermore, the weight loss intervention for obese stroke patients induced changes in the methylation patterns on WT1." (PMID 32392798, 2020). "WT1 staining revealed a decreased number of podocytes in stroke-induced rats." (PMID 31784544, 2019).
Thrombocytopenia (3 papers, 2016 to 2025). A reduction in the number of circulating thrombocytes. "Moreover, the expression increased during myelofibrotic transformation and high WT1 transcript levels could be linked to splenomegaly and thrombocytopenia and overexpression of WT1 was hypothesized to play an important role in the leukemic transformation of MPN." (PMID 32604862, 2020).
type 1 diabetes (3 papers, 2013 to 2025). "In addition, treatment of type 1 diabetes with a combination of resveratrol and human umbilical cord mesenchymal stem cells increased the number of podocytes and the expression of the podocyte-associated protein nephrin and Wilm’s tumor 1 (WT1), resulting in an amelioration of renal pathology." (PMID 41020857, 2025). "Thus in the present study we investigated urinary exosomal WT1 to confirm its role as a non-invasive biomarker for predicting early renal function decline in type-1 diabetic patients." (PMID 23544132, 2013).